TNF (tumor necrosis factor)
Diseases named in the same sentence as TNF in open-access papers (continued):
Sharing a sentence is not in itself a finding about the gene and the disease.
Insulin resistance (continued). "This evidence corroborates the hypothesis that male androgen levels could improve insulin resistance by reducing inflammatory cytokines, such as tumour necrosis factor-α (TNF-α), that are produced by adipocytes." (PMID 30616503, 2019). "TNF-α and IL-1β levels, counter regulated by IL-6 and soluble TNF-α receptor/soluble TNF-α receptor 2 (sTNFR1/sTNFR2) by TNF-α, correlate with impaired endothelium-dependent dilatation and induction of insulin resistance followed by high blood pressure, respectively." (PMID 31671730, 2019). "Therefore, we next examined the effects of FGF-1 on mice treated with TNF-α to induce insulin resistance." (PMID 31866871, 2019). "Furthermore, increased insulin resistance stimulates lipolysis and increases TNF-α production in the adipocytes." (PMID 31275421, 2019). "In addition, an acute TNF-α infusion in healthy humans leads to insulin resistance through impaired insulin signaling and decreased glucose uptake." (PMID 30863203, 2019). "Previous studies suggest that several cytokines and inflammatory mediators in the plasma are up-regulated in insulin resistance, including tumor necrosis factor-α (TNF-α), monocyte chemotactic protein-1 (MCP-1), C-reactive protein (CRP), and interleukin-6 (IL-6)." (PMID 31035653, 2019). "TNF-α is mostly derived from macrophages, which have been reported to promote insulin resistance." (PMID 30937278, 2019). "Consequently, the conditions for insulin resistance can be modeled by treating cells with insulin or TNF-α." (PMID 31635166, 2019). "Thus, TNFα can act locally in adipose tissue, which ultimately promotes insulin resistance in peripheral tissues." (PMID 30658634, 2019). "Moreover, adipocyte-derived IL-1β has been shown to directly induce, alone or in combination with TNFα, insulin resistance in hepatocytes via AMPK-ROS signaling and autophagy." (PMID 31507607, 2019). "The results showed the phosphorylation of tyrosine 632 of IRS-1 after treatment of cells with palmitate (to make the diabetic model of insulin resistance) and stimulation with insulin (to initiate the signal pathway) in TNF-α-downregulated cells was 45% (p < 0.05) higher than the normal cells." (PMID 30863203, 2019). "Exposure of cells to TNF-α causes inhibitory phosphorylation by receptor 1 of TNF-α (TNF-R1) to the serine residues of substrate 1 of the insulin receptor (IRS-1), favouring development of insulin resistance." (PMID 31275060, 2019). "Also, studies, in β-cells showed that OL exposure reduces the effect of TNF-α on insulin resistance; and in human endothelial cells, exposure to OL (unlike other FAs) down-regulated pro-inflammatory markers, including TNF-α." (PMID 30992393, 2019). "It is well-known that FFA activates the proinflammatory NF-κB pathway in skeletal muscle and increases the expression of several cytokines including TNF-α, IL-1β, and IL-6 in liver, resulting in insulin resistance including activation of c-Jun NH2-terminal kinase (JNK)." (PMID 31447776, 2019). "Furthermore, it is known that production of TNFα by hypertrophic and senescent adipocytes induces insulin resistance in ECs." (PMID 31013778, 2019). "Importantly, astaxanthin treatment restored TNFα- and palmitate-induced insulin resistance and decreased ROS generation of L6 muscle cells." (PMID 31814873, 2019). "Inflammation and insulin resistance are closely related and inflammatory cytokines such as TNF-α, interleukin (IL)-6, IL-1, and IL-8 may inhibit insulin signaling via multiple mechanisms." (PMID 31331342, 2019). "Studies of the TZD action in adipose tissue have shown that they alter leptin, inflammatory molecules, and circulating proteins (such as tumor necrosis factor alpha, TNF-α) expression, thus eventually contributing to the characteristic peripheral insulin resistance." (PMID 31658729, 2019).
Insulin resistance (continued). "Elevation in release of pro-inflammatory cytokines such as IL-6 and TNF-α may induce a low-grade inflammatory state and oxidative stress, eventually leading to insulin resistance." (PMID 31569345, 2019). "TNF-α is a pro-inflammatory cytokine, expressed by the oocytes, theca cells, GCs, and corpus luteum, playing an important role in regulating steroidogenesis, folliculogenesis, ovulation, luteinization, fertility and insulin resistance." (PMID 30946770, 2019). "TNFα stimulates lipolysis through attenuation of the insulin antilipolytic activity, increasing the release of free fatty acids, which are the major determinants of hepatic insulin resistance (IR) and lipogenesis, which culminates in NAFLD." (PMID 30813339, 2019). "Of note, recent in vitro data using preadipocytes revealed that the tripeptides IPP (Ile-Pro-Pro) and VPP (Val-Pro-Pro), which are derived from milk casein, enhance insulin sensitivity and contribute toward the prevention of insulin resistance in the presence of tumor necrosis factor." (PMID 31340611, 2019). "Finally, we focus on the consequences of inflammatory responses, in particular, the effect of TNF-α, IL-1β and IL-6 on insulin resistance." (PMID 31363792, 2019). "Significant correlation of IL-6 with TNF-α and insulin resistance was observed that may provide us a therapeutic target for preventing metabolic derangements from insulin resistance." (PMID 30635365, 2019). "Increased plasma levels of TNFα and IL6 are associated with insulin resistance (Shoelson, Herrero, & Naaz, 2007), inconsistent to observations made here where HFD‐fed Park2 KO mice were more insulin sensitive despite increased plasma TNFα and IL6 levels." (PMID 31724300, 2019). "To induce insulin resistance, we incubated L6 myotubes with TNF-α for 24 h." (PMID 29955954, 2019). "To test whether FGF-1 attenuates TNF-α-triggered insulin resistance, we next investigated the role of FGF-1 in TNF-α-induced hepatic insulin resistance." (PMID 31866871, 2019). "The authors found that acetyl-l-carnitine inhibited TNF-α-induced insulin resistance via activating AMPK signaling, thus increasing rates of skeletal muscle fatty-acid oxidation, leading to reduced malonyl-CoA and increased long chain fatty acyl-CoA flux into the mitochondria." (PMID 30644033, 2019). "Hence, it is obvious that the target genes of NF-кB, such as IL-1, TNF, and IL-6, and NF-кB itself, play vital roles in insulin resistance." (PMID 31842333, 2019). "We established tumor necrosis factor alpha (TNF-α)-induced insulin resistance skeletal muscle cell model and evaluated the effects of naringenin on reactive oxygen species (ROS) production, glucose uptake and glucose transporter type 4 (GLUT4) membrane translocation." (PMID 31591391, 2019). "The TNFα pro-inflammatory cytokine is known as a mediator of insulin resistance in PCOS." (PMID 32133054, 2019). "TNFα and IL6, which are both positively associated with insulin resistance (Hotamisligil, Shargill, & Spiegelman, 1993; Pickup, Mattock, Chusney, & Burt, 1997), were increased in plasma of HFD‐fed Park2 KO mice, inconsistent with the observed phenotype with regards to insulin sensitivity." (PMID 31724300, 2019). "TNF-α and IL-6 are correlated with insulin resistance, impaired glucose tolerance, and type 2 DM." (PMID 30915195, 2019). "Furthermore, anti-TNF-α treatment has been able to reduce insulin resistance in rheumatoid arthritis and in psoriasis." (PMID 31885787, 2019). "Our previous study showed that piceatannol could inhibit TNF-α-mediated inflammation and insulin resistance in 3T3-L1 adipocytes through Akt-dependent forkhead box O1 (FoxO1) signaling pathway." (PMID 31277394, 2019). "TNF-α is a mediator of insulin resistance through its ability to block the action of insulin." (PMID 31736870, 2019). "Other cytokines, such as TNF-α and IL-6, are also related to insulin resistance." (PMID 31030467, 2019).
Insulin resistance (continued). "TNFα is secreted by adipocytes and macrophages and reduces insulin transduction which could result in glucose metabolic disorders, insulin resistance and obesity possibly followed by the later stadium type 2 diabetes." (PMID 31849810, 2019). "TNFα promotes insulin resistance by the phosphorylation of insulin receptor substrate 1 (IRS1) on serine residues, via the activation of cellular stress-response kinases, including IκB kinase β (IKKβ), c-Jun N-terminal kinase (JNK), and protein kinase RNA-activated (PKR)." (PMID 30837902, 2019). "TNFα treatment of cultured adipocytes also results in a variable level of insulin resistance." (PMID 31781039, 2019). "We could assume that a pathway involving TNFα and insulin resistance could be a mechanistic link between T2D and depression, for example." (PMID 31349552, 2019). "TNF-α has also been reported as a major player in metabolic inflammation and insulin resistance." (PMID 31546972, 2019). "Insulin resistance was induced by treating L6 cells with 5 ng/ml TNF-α for 24 h." (PMID 29955954, 2019). "However, another study reported that overexpression of miR-181a-5p in adipocytes upregulated insulin-stimulated AKT activation and reduced TNFα-induced insulin resistance." (PMID 30717412, 2019). "TNF-α is known to be involved in the induction of insulin resistance." (PMID 31100973, 2019). "The 3T3-L1 adipocytes develop insulin resistance in response to insulin, TNF or saturated fatty acids, and transcriptional response to TNF begins within the first 1 h of the treatment, and changes in protein phosphorylation associated with insulin resistance can be detected as early as 6 h." (PMID 31635166, 2019). "In this study, we found that FGF-1 had positive effects on glucose intolerance, hepatic lipid accumulation, and insulin resistance, while it markedly repressed cytokine secretion (TNF-α and IL-6) in serum and reduced liver inflammation in diet-induced obesity (DIO) mice." (PMID 31866871, 2019). "However, M1-like macrophages, which produce pro-inflammatory mediators such as tumor necrosis factor α (TNF-α), accumulate in adipose tissue and promote insulin resistance in conditions of obesity." (PMID 29867212, 2018). "The binding of LPS with TLR4 could result in the stimulation of IKKβ and NF-κB and then increase the levels of downstream inflammatory factors (like TNF-α, IL-6, IL-1β, etc.), which promoted the insulin resistance in the tissue where they were produced." (PMID 30210342, 2018). "One key mechanism of relaying inflammatory processes between fat, liver, and gut during NAFLD is the release of cytokines such as IL-1β, IL-6, IFN-γ, and TNF-α, which aggravate local inflammation, thereby worsening insulin resistance and triglyceride accumulation in fat and liver tissue." (PMID 30405618, 2018). "Inflammatory cytokines such as tumor necrosis factor (TNF) can contribute to insulin resistance." (PMID 30548217, 2018). "Indeed, sortilin expression is differently altered in insulin resistance models induced by TNF-alpha or dexamethasone treatments." (PMID 30697159, 2018). "As we know, visfatin stimulates the synthesis of TNF and IL-6, which could suggest its adverse effect on the development of insulin resistance." (PMID 29516012, 2018). "TNF-α, as a predictor of insulin resistance in pregnancy, may suppress the function of peroxisome proliferator-activated receptor in adipocytes, thus inhibiting the secretion of adiponectin." (PMID 29895806, 2018). "Simultaneously, tumor necrosis factor α induces a peripheral insulin resistance." (PMID 30005711, 2018). "In addition, exercise promotes the inhibition of TNF-α, which is a key cytokine in the inflammatory process and in insulin resistance." (PMID 30405072, 2018). "Furthermore, production of TNFα by hypertrophic and senescent adipocytes is known to induce insulin resistance in ECs." (PMID 29464018, 2018).
Insulin resistance (continued). "Supporting this hypothesis is the finding that TLR4-mutant mice were resistant to hepatic steatosis, induction of TNF-α, lipid peroxidation, and insulin resistance compared with wild type mice." (PMID 29983886, 2018). "Those authors concluded that TNF-α serum levels might be related to insulin resistance and androgen excess." (PMID 30518097, 2018). "The levels of TNFα increase proportionally to adiposity and insulin resistance." (PMID 30366378, 2018). "Pro-inflammatory cytokines, particularly TNF-α, could enhance the serine phosphorylation of insulin receptor substrate-1, which induced insulin resistance." (PMID 30453687, 2018). "TNFα has been extensively reported to induce insulin resistance related to obesity." (PMID 29959379, 2018). "Furthermore, it has been established that inflammatory cytokines TNF-α and IL-6 inhibit the expression of insulin signaling mediators in adipose tissue leading to a worsening of whole-body insulin resistance and glucose intolerance." (PMID 30510798, 2018). "Furthermore, Metrnl illustrated a negative correlation with IL-6 and TNF-α in both CAD patients and also with BMI, insulin resistance, IL-6 and TNF-α in T2DM patients." (PMID 30212581, 2018). "In particular, we focused on gangliosides of ECs and we hypothesized that changes in the levels of cell surface gangliosides upon TNFα exposure contribute to insulin resistance in ECs." (PMID 29464018, 2018). "TNFα has been shown to act directly upon adipocytes and altered levels have been suggested to interfere with glycaemic homeostasis and promote greater insulin resistance as well as promoting endothelial dysfunction by inducing NF-κB signalling, NADPH activation and ROS production." (PMID 29238916, 2018). "Our results showed that bovine α-LAH supplementation improved systemic and adipose insulin resistance, downregulated TNF-α, IL-6, and MCP-1 mRNA expression and suppressed IKKα/β and MAPK signaling pathways in adipose tissues of obese C57BL/6J mice induced by HFD." (PMID 29473848, 2018). "In addition, pretreatment with BLEx ameliorated TNF-α-nduced insulin resistance with regard to 2-NBDG uptake and Akt phosphorylation." (PMID 29872751, 2018). "Specific cytokines produced by visceral adipose tissue, such as leptin, adiponectin and inflammatory factors including TNF-α and IL-6, might lead to insulin resistance." (PMID 29965999, 2018). "Indeed, TNF-α contributes to the pathogenesis of insulin resistance, T2DM, and abnormal adiposity or lipid disorders." (PMID 30914847, 2018). "Furthermore, neutralization of TNF-α activity improves insulin resistance and fatty liver disease in animals." (PMID 30024933, 2018). "Neutralizing TNF-α has been shown to reduce insulin resistance." (PMID 29527173, 2018). "Increased inflammatory markers, especially TNF-α, might promote insulin resistance, and alter expression of cytokines in adipose tissues which is considered an important link between MetS and insulin resistance." (PMID 29930690, 2018). "Besides, TNF-α suppresses the expression and activity of PPAR-γ in adipocytes and stimulates insulin resistance; NF-κB, activated by TNF-α and oxidative stress, reduces the transcriptional activity of PPAR-γ31,32." (PMID 29899429, 2018). "High expression of TNFα has been related with insulin resistance in obesity." (PMID 29959379, 2018). "Indeed, our results indicate that in the obese Zucker strain, which exhibits insulin resistance, the treatment with NP-1 aggravates transiently glucose intolerance, an effect that can be related to the high circulating TNFα." (PMID 29959379, 2018). "A recent study found that WBS application to the abdomen for 12 weeks was effective in reducing a proinflammatory state (as observed by TNF-α, adiponectin, and C-reactive protein levels), as well as fasting glycemia, insulin resistance, and visceral adiposity in obese diabetics." (PMID 30382930, 2018).
Insulin resistance (continued). "Accordingly, it has been demonstrated that TNF-α may induce insulin resistance by serine phosphorylation in IRS-1." (PMID 30134857, 2018). "Ultimately, we note that individuals with lipodystrophy have an increase in serum interleukins, keys of the inflammatory process, as IL-1β, TNF-α and IL-6 (p < 0.05 all), compared with healthy individuals, which can be the trigger to insulin resistance in this population." (PMID 29449893, 2018). "Accordingly, the rat model of T2DM exhibited dyslipidemia, insulin resistance, inflammatory response (TNF-α), and hepatic damage indicated by increased activity of serum transaminases and liver hypertrophy and apoptosis (increased gene expression of caspase-3)." (PMID 30186630, 2018). "Metformin acting as the first-line hypoglycemic drug improves hepatic insulin resistance mainly by decreasing hepatic expression of TNF-α, a cytokine that promotes insulin resistance, ameliorates hepatic steatosis and decreases aminotransferase levels, thus causes reversal of fatty liver." (PMID 29552319, 2018). "In addition, since mTORC1 and TNFα contribute to insulin resistance, the involvement of these two factors in tuberculosis pathogenesis provide a mechanistic explanation for the association between tuberculosis and insulin resistance." (PMID 30161232, 2018). "Hyperglycemia may stimulate the production of tumor necrosis factor-α from mononuclear cells that may result in inflammation and insulin resistance." (PMID 29766146, 2018). "Second, ferritin, which is an inflammatory factor, has been associated with the tumor necrosis factor-α (TNF-α) and interleukin-6 (IL-6), while elevated TNF-α and IL-6 may contribute to insulin resistance." (PMID 29949646, 2018). "In addition, fat cells secrete signaling factors, for example, interlukein-6 (IL-6) and tumor necrosis factor-α (TNF-α) which are involved in the development of insulin resistance." (PMID 29853887, 2018). "Moreover, through the release of free fatty acids (FFAs) and various adipokines such as leptin, adiponectin, resistin, PAI-1, Il-1b, and TNF-α, the hypertrophic adipocytes play a role in the progression of insulin resistance." (PMID 30510798, 2018). "Increased release from metabolically active abdominal fat of substantial adipokines, such as tumor-necrosis factor-α, free fatty acids, leptin and inflammatory markers, and reduced release of adiponectin, contribute to development of insulin resistance, compensatory and chronic hyperinsulinaemia." (PMID 30631750, 2018). "Another contributing factor to insulin resistance may be production of TNFα during infection, since this cytokine inhibits insulin receptor signaling." (PMID 30161232, 2018). "According to their physiological role, they have been divided into two groups: insulin resistance inducting factors such as resistin, tumor necrosis factor alpha (TNF-α), and interleukin 6 (IL-6) and insulin-sensitizing factors such as leptin, adiponectin, and visfatin." (PMID 29593647, 2018). "In addition, another study demonstrated that whole blueberry improved high fat diet-induced insulin resistance, and decreased TNF-α, IL-6, MCP-1, CD11c+, and inducible nitric oxide synthase (iNOS)." (PMID 28974032, 2017). "The proinflammatory cytokine TNFα is known to induce temporary insulin resistance in monogastrics." (PMID 28740504, 2017). "For example, grape powder extract could reduce both inflammation and insulin resistance mediated by TNF‐α in adipocytes." (PMID 28572933, 2017). "M1 macrophages are the primary source of TNF and seem to orchestrate insulin resistance." (PMID 27900559, 2017). "Moreover, AGL suppressed the TNF-α induced activation of NF-κB signaling pathway and its downstream inflammatory factor expression, suggesting a modulatory effect on insulin resistance." (PMID 28878680, 2017).